NOTCH2 (notch receptor 2)
Description:
Functions as a receptor for membrane-bound ligands Jagged-1 (JAG1), Jagged-2 (JAG2) and Delta-1 (DLL1) to regulate cell-fate determination. Upon ligand activation through the released notch intracellular domain (NICD) it forms a transcriptional activator complex with RBPJ/RBPSUH and activates genes of the enhancer of split locus. Affects the implementation of differentiation, proliferation and apoptotic programs (By similarity). Involved in bone remodeling and homeostasis. In collaboration with RELA/p65 enhances NFATc1 promoter activity and positively regulates RANKL-induced osteoclast differentiation. Positively regulates self-renewal of liver cancer cells.
Synonyms: hN2; AGS2; HJCYS
Tractability: Small molecule: it has a binding pocket of medium quality. Antibody: a drug acting on it is in phase 2 or 3 trials; UniProt places it where antibodies can reach, with high confidence; its Gene Ontology location is reachable by antibodies, with high confidence; UniProt predicts a signal peptide or a membrane-spanning region; the Human Protein Atlas places it where antibodies can reach. PROTAC: UniProt records ubiquitination sites on it; ubiquitination databases record sites on it; its protein half-life has been measured; a small molecule that binds it is known.
Target class: Membrane receptor
Gene: Protein-coding gene on chromosome 1 (119,911,553 to 120,100,779, reverse strand). Ensembl gene ENSG00000134250.
Subcellular location: Cell membrane (Notch 2 extracellular truncation); Nucleus (Notch 2 intracellular domain); Cytoplasm
Subcellular location (Human Protein Atlas): Nucleoplasm; Plasma membrane; Golgi apparatus
Pathways (Reactome):
Signal Transduction: NOTCH2 Activation and Transmission of Signal to the Nucleus; NOTCH2 intracellular domain regulates transcription; NOTCH4 Intracellular Domain Regulates Transcription; Pre-NOTCH Processing in Golgi; Pre-NOTCH Processing in the Endoplasmic Reticulum; Pre-NOTCH Transcription and Translation
Developmental Biology: Differentiation of naive CD4+ T cells to T helper 2 cells (Th2 cells)
Disease: Defective LFNG causes SCDO3
Gene expression (Transcription): Notch-HLH transcription pathway
Gene Ontology:
Molecular function: protein binding; transcription coactivator activity; signaling receptor activity; calcium ion binding; enzyme binding; NF-kappaB binding
Biological process: animal organ morphogenesis; atrial septum morphogenesis; bone remodeling; cellular response to tumor cell; intracellular signal transduction; negative regulation of gene expression; Notch signaling pathway; positive regulation of ERK1 and ERK2 cascade; positive regulation of keratinocyte proliferation; positive regulation of miRNA transcription; positive regulation of Ras protein signal transduction; positive regulation of smooth muscle cell differentiation; positive regulation of transcription by RNA polymerase II; pulmonary valve morphogenesis; regulation of osteoclast development; apoptotic process; atrioventricular node development; axon guidance; cell fate determination; hemopoiesis; marginal zone B cell differentiation; negative regulation of apoptotic process; nervous system development; cardiac septum morphogenesis; cell differentiation; and 12 more
Cellular component: cell surface; cytoplasm; membrane; nucleoplasm; nucleus; plasma membrane; receptor complex; endoplasmic reticulum membrane; extracellular region; Golgi membrane; cilium
Genetic constraint (gnomAD): Loss-of-function variants: 24 observed, 223.05 expected, observed/expected ratio (o/e) 0.11, 90% interval 0.077 to 0.15. The upper end of that interval is the gene's LOEUF score, 0.15, which puts it in group 1 of 6, group 1 being the genes least tolerant of losing a copy. Missense variants: 2,225 observed, 3,155.1 expected, observed/expected ratio (o/e) 0.71, 90% interval 0.68 to 0.73. Synonymous variants: 1,056 observed, 1,155.4 expected, observed/expected ratio (o/e) 0.91, 90% interval 0.87 to 0.96.
Gene-disease validity (ClinGen):
ClinGen rates the evidence that NOTCH2 causes each of these diseases.
acroosteolysis dominant type (autosomal dominant): Definitive. A rare genetic osteolysis syndrome resulting from protein-truncating variants in exon 34 of the NOTCH2 gene.
Alagille syndrome (autosomal dominant): Definitive.
Cancer hallmarks: invasion and metastasis (promotes); escaping programmed cell death (promotes); proliferative signalling (promotes); suppression of growth (promotes)
Homologues: Orthologues: chimpanzee NOTCH2 (99% identical), macaque NOTCH2 (99% identical), pig NOTCH2 (95% identical), dog NOTCH2 (95% identical), rabbit NOTCH2 (95% identical), guinea pig NOTCH2 (93% identical), mouse Notch2 (93% identical), rat Notch2 (93% identical), tropical clawed frog notch2 (69% identical), zebrafish notch2 (55% identical), zebrafish si:ch73-281k2.5 (7% identical). Paralogues in human: NOTCH1 (54% identical), NOTCH3 (49% identical), SNED1 (15% identical), NOTCH2NLR (10% identical), NOTCH2NLC (10% identical), NOTCH2NLB (9% identical), NOTCH2NLA (9% identical).
Diseases named in the same sentence as NOTCH2 in open-access papers:
NOTCH2 is named in the same sentence as 323 diseases in open-access papers, as found by Europe PMC text mining. Sharing a sentence is not in itself a finding about the gene and the disease. The quoted sentences say what the papers report.
breast cancer (88 papers, 2009 to 2026). A primary or metastatic malignant neoplasm involving the breast. "Upregulation of JAG1 and FAT2 has furthermore been linked to poor prognosis in breast cancer, and a Jagged-1/Notch2/PDGFR stroma–epithelial mechanism has been described in a poor prognosis fibroblast subset." (PMID 38172915, 2024). "Here, we have crossed conditional knockout Notch1 or Notch2 alleles into an established mouse mammary tumour model." (PMID 37686600, 2023). "Hunter’s group conducted a large genome-wide scan plus two stages of follow-up in 10,263 controls and 9,335 cases and found conclusive statistically significant association of NOTCH2 related rs11249433 with breast cancer." (PMID 34257585, 2021). "In the overall analysis, only rs11249433 SNP that is in linkage disequilibrium with NOTCH2 exhibited statistically significant association with breast cancer susceptibility." (PMID 34257585, 2021). "As observed for the overall analysis, the rs11249433 (NOTCH2) SNP was found to be significantly associated with early onset (≤53 years of age at diagnosis) of breast cancer." (PMID 34257585, 2021). "On the other hand, NOTCH2, encoded for the receptor of Notch signaling pathway, was reported to suppress tumor growth in human breast cancer xenografts." (PMID 33919109, 2021). "Although mutation of NOTCH1 or NOTCH2 only occurs in a small proportion of breast cancer cases, inclusion of cases harboring both mutation and overexpression accounts for 30% of poor-prognosis TNBC cases." (PMID 33750924, 2021). "In our comparison by age at diagnosis, we observed strong association of NOTCH2 rs11249433 with increased risk of early onset of breast cancer." (PMID 34257585, 2021). "The GA genotype of NOTCH2 related rs11249433 SNP conferred about 4.7 fold higher risk of developing carcinoma of the breast before or till the age of 53 years relative to those having GG genotype (OR = 4.692, χ2 = 7.26, p = 0.00707)." (PMID 34257585, 2021). "Parr and colleagues analyzed Notch-1 and Notch-2 mRNA and protein expression levels in normal and breast cancer tissues also in association whit clinicopathological parameters." (PMID 31379945, 2019). "Mutations in Notch2 show increased incidence in breast cancer, and in addition to the TCGA database new mutations have been found." (PMID 30515368, 2018). "Consistent with this, we observed that a γ-secretase inhibitor treatment reversed these pro-metastatic functions of Notch2 by disrupting the Notch pathway in associated breast cancer cells." (PMID 27462787, 2016). "Low Notch activity leads to hyperproliferative activity in breast cancer and mutation in NOTCH2 causes Hajdu-Cheney syndrome." (PMID 24969172, 2014). "Recently, a study reported a positive association of NOTCH2 mRNA expression with the breast cancer risk allele of rs11249433." (PMID 23544014, 2013). "This is the first study to show that the expression of NOTCH2 differs in subgroups of breast tumors and by genotypes of the breast cancer-associated SNP rs11249433." (PMID 20482849, 2010). "Investigations on the association of NOTCH1 rs3124591, NOTCH3 rs1043994, and NOTCH4 rs3830041 with the risk of human cancers are rare, however, several studies have shown a link between NOTCH2 related rs11249433 and increased risk of breast cancer especially in women of European ancestry." (PMID 34257585, 2021). "Besides mutations in Notch1 and Notch2, approximately 50% of all human breast cancers show loss of Numb signaling, due to ubiquitination and degradation of Numb, which act as a tumor suppressor." (PMID 34572582, 2021).
breast cancer (continued). "Moreover, it has been demonstrated that the NOTCH2 rs11249433 exhibited a stronger association with the development of breast cancer especially with ER-positive tumors compared to ER-negative tumors." (PMID 34257585, 2021). "Our finding of a significant association of NOTCH2 rs11249433 with the risk of breast cancer suggests that Saudi population may be closer to the Europeans than to Africans or Asians in terms of genetic susceptibility to breast cancer." (PMID 34257585, 2021). "However, a strong association of rs11249433 which is in close proximity to NOTCH2 was observed with breast cancer susceptibility especially with those having an early onset of the disease." (PMID 34257585, 2021). "For examples, SNPs in NOTCH1 and NOTCH2 are associated with risk of breast carcinoma." (PMID 34257585, 2021). "Notch2 signal implication was demonstrated by immunophenotyping the endosteal niche-associated cancer cells and upon co-culture with sorted endosteal niche cells, which inhibited breast cancer cell proliferation in a Notch2-dependent manner." (PMID 31239543, 2019). "Gain-of-function mutations in NOTCH1 and NOTCH2 are found in breast cancer, and NOTCH1 translocations are also found in ductal carcinoma in situ (DCIS), which may be considered an early stage in breast cancer development." (PMID 30388742, 2018). "Treatment was also related to increasing levels of NOTCH2, which is a relevant protein in breast cancer propagation and associated with a poor prognosis, indicating the important ability of cholesterol and mevalonate to support the propagation and stemness of breast cancer cells." (PMID 32751976, 2020). "Recently, a multistage genome-wide association study (GWAS) of breast cancer identified a new breast cancer susceptible locus at 1p11.2 (the marker SNP: rs11249433) in populations of European descent, which resides in a large linkage disequilibrium (LD) block neighboring NOTCH2 and FCGR1B." (PMID 21738711, 2011). "High levels of Notch-1/2/3/4 have been identified in breast cancer, where Notch-2 is considered as a tumor suppressor, and in cervical cancer in correlation with a poor overall survival." (PMID 38314334, 2024). "Overexpression of NOTCH2 has been identified in multiple cancer types including breast cancer, lung squamous cell carcinoma, leukemia, ovarian cancer, and colorectal cancer." (PMID 39199357, 2024). "Among the six fusions identified in breast carcinoma samples of the 38 samples examined, three involved NOTCH2, and one each involved FGFR3, NTRK3, and BRAF." (PMID 38800398, 2024). "Another in vitro study demonstrated that BITC-exposed human breast cancer cells also increased the level of Notch1, Notch2, and Notch4, and the Notch activation was accompanied by induction of secretase complex component Nicastrin." (PMID 37190316, 2023). "Evidence has shown that the Notch2 receptor has been targeted by several plant products, and one such study highlights that Notch2 activation by BITC impedes its inhibitory effect on breast cancer cell migration." (PMID 37190316, 2023). "In breast cancer, elevated NOTCH1 expression is significantly associated with poor-prognosis breast cancer, while NOTCH2 expression is associated with good-prognosis breast cancer." (PMID 37686600, 2023). "Breast cancer cells that interact with spindle-shaped N-Cadherin+ Osteoblasts (SNOs) are recognised to become dormant through a Notch2-dependent mechanism." (PMID 35267624, 2022). "These locations are associated with breast cancer cytogenetics and pathology and harbor genes (NOTCH2 and RCP, respectively) associated with breast cancer etiology." (PMID 35992833, 2022). "Notch2 overexpression predicts better overall survival in women with breast cancer, which is completely different from Notch1." (PMID 36139447, 2022).
breast cancer (continued). "Inhibition of the Notch2 pathway has been suggested to reactivate and mobilize dormant breast cancer cells from the endosteal niche by releasing the interaction between dormant cancer cells and SNOs." (PMID 35994202, 2022). "Different rearrangements in Notch1 and Notch2 were found in a subset of breast cancer patients and cell lines, mostly triple negative breast cancers." (PMID 34572582, 2021). "Lakshminarayan and collaborators reported several Gal3 cell-surface binders in mouse mammary tumor epithelial cells, including Notch2." (PMID 34222228, 2021). "Our models also showed good results on predicting mutations of RB1 (AUC 0.852), CDH1 (AUC 0.776), NF1 (AUC 0.768), NOTCH2 (AUC 0.740) in breast cancer." (PMID 34556802, 2021). "AP-2 transcription factors interact with the promoter of both Notch 1 and 3 in P19 embryonal carcinoma cells and with the Notch 2 promoter in MCF-7 breast cancer cells." (PMID 34795288, 2021). "We show that both Notch-1 and Notch-2 are upregulated in cancer samples compared to healthy tissue, thus emphasizing the important role and dysregulation of the Notch pathway in breast cancer." (PMID 32245259, 2020). "The less well-characterised role of Notch 2 in breast cancer is somewhat ambiguous, with several in vitro studies suggesting a protumourigenic role and other in vivo studies reporting a tumour-suppressive role." (PMID 32575680, 2020). "Further work is required to definitively define the role of Notch receptors, in particular Notch 2, in the breast cancer setting." (PMID 32575680, 2020). "More interestingly, numerous studies suggested that Notch2 overexpression is related to a greater chance of survival of breast cancer patients." (PMID 31379945, 2019). "Some studies describe NOTCH2 as a tumor suppressor gene in breast cancer while as an oncogene in bladder cancer promoting cancer growth and metastasis through epithelial–mesenchymal transition (EMT), which process is fully consistent with our findings." (PMID 31159827, 2019). "Altogether, these results confirmed both the relevance of the Notch2 pathway in the cellular dormancy and the role of the bone in the metastatic dissemination of breast cancers to vital visceral organs." (PMID 31239543, 2019). "Knockdown of Notch2 protein causes inhibition of cell migration, thus, the effects of zerumbone on Notch2 expression were investigated and exposure of breast cancer cells to the compound resulted in increased transcriptional activation of Notch2." (PMID 31394732, 2019). "Notch2 represents a key determinant of breast cancer cellular dormancy and mobilisation in the bone microenvironment." (PMID 31239543, 2019). "In agreement with those preclinical results, at the end of her presentation she showed that in breast cancer patients, high expression of Notch2 is correlated with better prognosis, thus potentially representing a new prognostic marker for recurrence." (PMID 30867009, 2019). "Evidence for its oncogenic role came from studies on cultured breast cancer cells where knockdown of Notch2 leads to the inhibition of cell migration and cancer stem cell survival." (PMID 31379945, 2019). "Since NOTCH2 is considered as a tumor suppressor gene in certain breast cancer cell lines, we additionally tested HCC38 and MDA-MB-468 breast cancer cells for their NOTCH activity and sensitivity to gliotoxin." (PMID 28736522, 2017).